CXCR4 (C-X-C motif chemokine receptor 4)
Diseases named in the same sentence as CXCR4 in open-access papers (continued):
Sharing a sentence is not in itself a finding about the gene and the disease.
cancer (continued). "Metabolism reprogramming represents another hallmark of cancer, but few studies have investigated the potential effects of CXCL12 signaling through CXCR4 or ACKR3 on metabolic shifts in cancer cells." (PMID 35681470, 2022). "For example, pharmacologic depletion of CXCR4 and immunotherapy inhibited cancer progression in a mouse model of PDAC." (PMID 36143975, 2022). "Altogether, these findings clearly suggest that successive T22-DITOX-H6 administration effectively eliminates CXCR4+ invasive cancer cells endowed with metastatic potential." (PMID 35456719, 2022). "These pathways include JAK/STAT Signaling, Renin-Angiotensin Signaling, Molecular Mechanisms of Cancer, IL-8 Signaling, CXCR4 Signaling, LPS-Stimulated MAPK Signaling, EGF Signaling, PEDF Signaling, NF-κB Activation by Viruses, and B Cell Receptor Signaling." (PMID 34983392, 2022). "lncHILAR was also reported to be secreted by hypoxic cancer cells and transferred to normoxic cancer cells through exosomes to activate the miR-613/206/1-1-3p/Jagged-1/Notch/CXCR4 axis, thereby promoting cell invasion and metastasis." (PMID 35444652, 2022). "The physiological functions of CXCR4 are not only critical for development and homeostasis but also for the survival of cancer cells." (PMID 35406582, 2022). "Blocking of CXCR4 function by a monoclonal antibody clearly inhibited cancer cell proliferation, motility and invasion." (PMID 36103228, 2022). "Compared to free Peptide R, liposomes led to increased stability in vivo and inhibited CXCR4 more efficiently by generating multi-valent binding ligands, thus inhibiting the metastasis of cancer cells." (PMID 35893797, 2022). "Previous studies have verified that CXCR4 antagonists produce therapeutic effects in many diseases varying from cancers to human immunodeficiency virus (HIV)." (PMID 35729596, 2022). "Immunohistochemistry and histopathological analyses were used to study the CXCR4 expression in the cancer cells, to evaluate the effect of the nanotoxin treatment, and its potential off-target toxicity." (PMID 35456719, 2022). "CSC can also overexpress the chemokine receptor C-X-C motif chemokine receptor 4 (CXCR4) in many cancer types by using the typical pathway of hematopoietic stem cells (HSCs)." (PMID 35414025, 2022). "The C-X-C motif chemokine receptor 4 (CXCR4) has been established as a potential target for various applications in oncology and interacts with crucial factors for cancer spread, such as angiogenesis or further involvement leading to therapeutic resistance." (PMID 35954476, 2022). "Even though it did not reveal clinical remissions due to the short period, it provides early indications of the possibility of an early anti-cancer effect mediated by CXCR4 inhibition." (PMID 35615089, 2022). "Patients with a high pCXCR4/CXCR4 TIC ratio in primary cancer biopsies showed a significant longer RFS during the first two years (p = 0.025)." (PMID 35397601, 2022). "Clinical trials have provided interesting data to consider CXCR4 antagonists as an alternative in cancer therapy in multicenter, randomized, and even phase II studies." (PMID 36613922, 2022). "CXCL12, the ligand of CXCR4, which is secreted from activated fibroblasts, was proven to stimulate cancer cell migration and promote cancer cell invasion through EMT transition, and is also elevated in CAF1 compared to NF1/NF2." (PMID 35853880, 2022). "The chemokine receptor CXCR4 is widely expressed on range of haematological and solid tumours, as well as cancer stem cells." (PMID 35205725, 2022). "Noteworthy, the CXCL12/CXCR4/CXCR7 axis is functionally involved in cancer cell proliferation, survival, and migration." (PMID 36568151, 2022). "Reportedly, overexpression of CXCR4 has been detected in a wide range of cancer, including cervical, colon, gastric, melanoma, ovarian, pancreatic, renal, and hematological malignancies." (PMID 35236304, 2022).
cancer (continued). "Preclinical studies proved that blocking the CXCR4/CXCL12 axis with plerixafor (AMD3100), CXCR4-specific peptides, or monoclonal antibodies reduced cancer growth and metastasis while promoting sensitization to chemotherapy, radiation, or immunotherapy." (PMID 35336029, 2022). "CD20 and the chemokine receptor CXCR4 are critical for B cell trafficking and are molecular targets for cancer immunotherapies." (PMID 36353222, 2022). "The chemokine stromal cell derived factor-1 (SDF-1) interacts with its only receptor CXCR4 and plays an important role in the biological behavior of cancer cells." (PMID 35545781, 2022). "In a pilot study with esophageal cancer patients, [68Ga]Ga-Pentixafor imaging was feasible; however, heterogeneous CXCR4 expression limited its application in this cancer type." (PMID 35788730, 2022). "CXCR7 and CXCR4 are G protein-coupled receptors (GPCRs) that can be stimulated by CXCL12 in various human cancers." (PMID 36077241, 2022). "The nanoparticles blocked the interaction between cancer cells and stroma to interfere with cancer progression through blocking the binding between CXCR4 and C-X-C motif chemokine ligand 12 (CXCL12) with CXCR4 antagonists." (PMID 35875197, 2022). "CXCR4 is overexpressed in various cancers, contributing to their rapid growth, metastasis, chemo-resistance, and poor prognosis." (PMID 35336029, 2022). "CXCR4, a type of chemokine receptors, is widely expressed in malignant tumors and its oncogenic role has been confirmed in various cancers." (PMID 35729596, 2022). "The overexpression of the CXCL12/CXCR4 complex was found to be a marker for bone metastases in many cancer types." (PMID 36497192, 2022). "The C-X-C motif chemokine receptor 4 (CXCR4) has been recognized as a potential target for various applications in oncology and moderates crucial factors for cancer spread, such as angiogenesis or further involvement leading to therapeutic resistance." (PMID 35674738, 2022). "CXCR4 is highly expressed in tumors by many cell types, and several clinical trials with CXCR4 inhibitors are ongoing in cancer patients." (PMID 35158948, 2022). "The development of small‐molecule inhibitors, antagonist peptides, and antibodies against CXCR4 has provided new opportunities to combat various cancers." (PMID 36054080, 2022). "Upon repeated T22-DITOX-H6 administration, the number of CXCR4+ cancer cells was significantly reduced." (PMID 35456719, 2022). "The CXCL12/CXCR4 interaction promotes the early event of primary cancer cells expressing CXCR4 migrating towards CXCL12 to the liver." (PMID 35145271, 2022). "• We observed a significant association between high pCXCR4/CXCR4 TIC ratio and better RFS in primary cancer biopsies, especially during the early postoperative follow-up and independent of known risk factors for recurrence." (PMID 35397601, 2022). "CXCL12, binding to its receptor CXCR4, has been reported to be related to the prognosis of several types of cancer and promote cancer progression in preclinical models, including IBD and CRC." (PMID 35363937, 2022). "Certain surface molecules on cancer cells, such as CXCR4, have been shown to be involved in interstitial flow-mediated invasion in various cancers." (PMID 35740673, 2022). "A number of clinical trials of the combination of a CXCR4 inhibitor with anti-PD-1/PD-L1 therapy are currently underway in several types of cancer." (PMID 36012588, 2022). "Recently, the expression of CXCR4 was found to be involved in cancer stem cells self-renewal and the generation and maintenance of the perivascular stem cell niche." (PMID 35571062, 2022). "Combined therapeutic targeting of CXCR4 and PD-1 appears promising and is under phase 1 and 2 clinical trial evaluation for various cancers (NCT04058145, NCT03628859, NCT04177810, NCT02826486, NCT03168139, and NCT04177810)." (PMID 35797269, 2022).
cancer (continued). "We have explored here the applicability of the DT TD as a functional component in self-assembling protein-only nanoparticles targeted to the cell surface cytokine receptor CXCR4, which is a relevant molecular marker for anti-cancer drug targeting." (PMID 36559138, 2022). "Several other CXCR4 antagonists are being tested for cancer treatment in preclinical and clinical settings." (PMID 35884382, 2022). "T22-DITOX-H6 includes the CXCR4 ligand T22, fused to the cytotoxic domain of the diphtheria toxin, which is able to selectively internalize and eliminate CXCR4+ HNSCC cancer cells." (PMID 35456719, 2022). "Chemokine receptor antagonist (CRA) drugs such as maraviroc (CCR5 antagonist) or plerixafor (CXCR4 antagonist) have shown a role in the suppression of cancer cell proliferation, migration, and metastasis." (PMID 36613922, 2022). "CXCR4 is a marker of normal and malignant stem cells, and CXCL12/CXCR4 signaling is a crucial regulator of stem cell trafficking and cancer cell metastasis." (PMID 36591565, 2022). "A growing body of literature reports on the upregulation of C-X-C motif chemokine receptor 4 (CXCR4) in a variety of cancer entities, rendering this receptor as suitable target for molecular imaging and endoradiotherapy in a theranostic setting." (PMID 35674738, 2022). "HIF-1α derived from M2 macrophages elevates the secretion of CXCR4 in cancer cells to promote colorectal liver metastasis." (PMID 35251974, 2022). "CXCR4 is overexpressed in more than 20 human cancer types and correlated with advanced disease status and poor prognosis." (PMID 36465350, 2022). "For example, C–X–C chemokine receptor 4 (CXCR4) is overexpressed in over 23 different types of cancer and is more prevalent in malignant cancer tissue." (PMID 35701677, 2022). "In this study, we found a statistically significant difference in the mean mRNA expression level of CXCR4 between cancer tissue and corresponding normal gastric mucosa." (PMID 35877436, 2022). "Activation via binding of SDF-1 initiates different signaling pathways resulting in proliferation, chemotaxis, and site-specific metastasis of CXCR4-expressing cancer cells." (PMID 36419107, 2022). "The cancer-stroma interactions mediated by CXCL12/CXCR4 and E-selectin, which facilitate the formation of metastases in other anatomical sites, such as lymph nodes and lungs, are discussed elsewhere." (PMID 36568151, 2022). "Overexpression of miR-125b powerfully triggers EMT and cancer invasion, thereby enhancing the expression of CXCR4." (PMID 35836256, 2022). "Among the interface genes in the IBT_Her2+_TNBC module, CXCR4 is a known cancer-related chemokine receptor gene." (PMID 35992864, 2022). "In this context, targeting the chemokine receptor 4 (CXCR4) has emerged as a promising approach in cancer treatment." (PMID 35120582, 2022). "Among these receptors, CXCR4 has been the focus of much effort, due to its involvement in many different cancer types." (PMID 35159113, 2022). "The aim of this study was to estimate the effect of CXCR4 knockdown-mediated reduction of cancer stem cells (CSCs) and epithelial–mesenchymal transition (EMT) stemness and enhancement of chemotherapy sensitivity in EOC." (PMID 35681259, 2022). "In this study, C‐X‐C motif chemokine receptor 4 (CXCR4), a typical target protein in cancer therapy, was selected as a representative target of ex vivo genome editing." (PMID 35595716, 2022). "It exhibits strong binding affinity to overexpressed CXCR4 in cancer cells with a Kd of 1.19 μM, determined using Elisa." (PMID 35145271, 2022). "Our objective in this study was to characterize endogenous cancer cell PD-1 and CXCR4 interactions that contribute to the overall cytotoxicity from these combination regimens." (PMID 35797269, 2022). "The highest level of CXCR4 expression occurred at one-hour post exposure to isoproterenol at 20 μM which has been observed in previous works on the stimulation of cancer cells with beta agonists." (PMID 35259193, 2022).
cancer (continued). "CXCR4 mRNA translates into the CXCR4 protein and promotes cancer progression by inducing the transforming protein RhoA, which enhances cytoskeleton construction, cell adhesion, and migration." (PMID 35632763, 2022). "A rhenium(I) tricarbonyl complex was conjugated to a derivative of T140, a known antagonist of CXCR4 and a chemokine receptor which is overexpressed in cancer cells." (PMID 35701677, 2022). "To evaluate the prognostic and predictive significance of CXCR4 and pCXCR4 we calculated the Uni- and Multivariate Hazard Cox regression analysis in primary and recurrent cancer biopsies." (PMID 35397601, 2022). "To improve HCC targeting, we modified the NPs with the targeting peptide CTCE-9908 (KGVSLSYRCRYSLSVGK; referred to as CTCE), which is specific to CXCR4, a chemokine receptor that is upregulated in cancer cells and is a validated selective target in HCC29,30." (PMID 35140208, 2022). "With the development of nanotechnology, nano-formulations of CXCR4 antagonists are being increasingly applied for the treatment of various cancers and aim to improve drug stability and bioavailability for better therapeutic effects." (PMID 35893797, 2022). "In vivo, these cells metastasize because CXCR4-positive cancer cells selectively survive by an anti-apoptotic effect and by the secretion of CXCL12 by stellate liver cells." (PMID 35406582, 2022). "Several chemokine receptors, namely CCR4, CCR7, CCR9, and CXCR4, are substantially expressed in oncovirus-induced cancer cells." (PMID 35159113, 2022). "In cancer cells, however, chemokine receptors (e.g., CXCR4) have been shown to support an invasive phenotype." (PMID 35804822, 2022). "This nanocarrier was previously developed in our group, and it targets the CXCR4 receptor, and therefore the CXCR4-overexpressing cancer cells." (PMID 35884987, 2022). "Of the three prognostic DE-ATGs, CXCR4 was found to be significantly upregulated and suggested poor prognosis in many cancer types, including GC." (PMID 36173625, 2022). "Accordingly, inhibitors of the SDF-1 receptor (CXCR4) or the MCP-1 receptors effectively abolished the stimulatory effects of Gal-8 on cancer cell migration toward osteoblasts." (PMID 35015084, 2022). "New alternatives for these antagonists, such as dual CXCR4/CCR5 antagonists or combined therapy in association with immunotherapy, need to be studied in cancer therapy." (PMID 36613922, 2022). "CXCR4 is a receptor that is highly expressed in over than 20 cancer types and is a major co-receptor for cellular entry of human immunodeficiency virus." (PMID 35335871, 2022). "Due to its ubiquitous downstream effects on cancer survival, CXCR4 serves as a valuable candidate therapeutic target for PDAC." (PMID 35797269, 2022). "CXCR4 has become a target of interest in IO therapies due to its immunogenic effects and overexpression in many cancers." (PMID 35797269, 2022). "CXCR4 is also overexpressed in more than 20 cancer types compared to the normal organs, including HNSCC." (PMID 35456719, 2022). "Meanwhile, TGF-β activated the fibroblasts to form cancer-associated fibroblasts (CAFs) that secrete higher CXCL12 levels, which bound to its cognate receptor CXCR4 on M2 macrophages." (PMID 35853880, 2022). "This material mediates the selective delivery of covalently attached chemical drugs and of proapoptotic peptides, placed as GFP fusions, into CXCR4+ cancer cells, in vitro and in vivo." (PMID 36559138, 2022). "The CXCL12/CXCR4 axis has been reported to be involved in a variety of biofunctions of cancers via stimulating ERK1/2." (PMID 35860597, 2022). "CXCL12 is a type of autocrine/paracrine growth factor for a variety of cancers and is capable of increasing the level of CXCR4 in triple-negative breast cancer (TNBC) cells." (PMID 35236304, 2022). "Blocking the CXCR4/CXCL12 signalling axis promotes T-cell accumulation and acts synergistically with anti-PD-L1 to cause cancer regression." (PMID 36284271, 2022).
cancer (continued). "Being widely expressed within the human body, the CXCR4 upregulated state has been reported in over 20 types of human malignant tumors such as breast, prostate, lung, ovarian, and brain cancer." (PMID 35745762, 2022). "Previous studies have shown that miR-494-3pplays a cancer suppressor role in SS through modulating CXCR4." (PMID 36003502, 2022). "CXC chemokine receptor 4 (CXCR4) is a G-protein-coupled receptor highly expressed in different human carcinomas, at all stages of the epithelial–mesenchymal transition, invasion, or metastasis, and has been related to a poor prognosis." (PMID 36613922, 2022). "The present review describes the current therapeutical perspectives of HIVrCR, CCR5, and CXCR4 antagonist drugs in treating carcinomas." (PMID 36613922, 2022). "Cisplatin can increase the expression of CXCR4, which can promote the proliferation of cancer stem cells and enhance drug resistance, forming a vicious circle." (PMID 33829065, 2021). "Well known for its central role in cancer progression and distribution, CXCR4 is highlighted in this review with regard to its biology, prognostic and predictive relevance and therapeutic implications in WM." (PMID 33273682, 2021). "The SDF-1/CXCR4 axis has been demonstrated to activate the transcription factor NF-κB, which affects the proliferation and survival of cancer cells." (PMID 34531745, 2021). "In cancer progression and metastasis, the expression of chemokine receptor 4 (CXCR4) and chemokine receptor 7 (CCR7) is of particular importance." (PMID 34685420, 2021). "CXCL12 acts as a ligand for CXCR4 and plays a crucial role in autocrine/paracrine signaling in several cancers." (PMID 35053027, 2021). "The CXCR4 axis plays a pivotal role in the regulation of cancer cell dissemination and colonization of distant organs." (PMID 34107168, 2021). "Further, ITCH can inhibit the expression of C-X-C motif chemokine receptor 4 (CXCR4), which promotes the metastasis of cancer cells." (PMID 33435156, 2021). "The main signaling axis that is affected by CXCR4 mutations promote enhanced AKT and subsequent MAPK 1/2 signaling, resulting in sustained survival signals for cancer cells." (PMID 33273682, 2021). "CXCR4 is another major trafficking receptor for MDSCs and several clinical trials of CXCR4 inhibitors have been conducted for the treatment of some cancers." (PMID 34885241, 2021). "These factors mediate activation of TGF-β, cyclin B1, matrix metalloproteinase-1 and CXCR4, all related to the proliferation and metastasis of cancer cells." (PMID 33390169, 2021). "The CD133+/CXCR-4+ subpopulation of cancer cells was found to possess migratory potential and induce metastasis of pancreatic cancer." (PMID 34885003, 2021). "Although the chemokine receptor CXCR4 has been shown to be expressed by most cancers, it was originally reported that CXCR4 regulates the migration of lymphocytes into the inflammatory tissues." (PMID 34833360, 2021). "Inhibition of CXCR4 is a promising strategy for the treatment of several disorders such as cancers, HIV, and inflammatory diseases." (PMID 34552197, 2021). "This peptide, as an amino-terminal protein fusion, also targets these constructs to selectively bind and penetrate CXCR4-overexpressing cancer cells." (PMID 34834337, 2021). "The prognosis of cancer patients who have an overexpression of CXCR4 in cancer cells is poor, and these patients are at a high risk of recurrence." (PMID 34452282, 2021). "They assessed the results of CP treatment on the migration of cancer cells and its correlation with the chemokine receptor 4 (CXCR4), which is considered a biomarker of cancer metastasis." (PMID 34884588, 2021). "In the TME, cancer and stromal cells also express C-X-C motif chemokine receptor 4 (CXCR4) and produce its ligand C-X-C motif ligand 12 (CXCL12) to sustain CSC self-renewal and to recruit regulatory DCs." (PMID 34235155, 2021).